APC (APC regulator of Wnt signaling pathway)
Diseases named in the same sentence as APC in open-access papers (continued):
Sharing a sentence is not in itself a finding about the gene and the disease.
breast cancer (continued). "Using patient samples and a panel of human breast cancer cell lines, we found no significant trend between APC and either MDR1 or MRP1." (PMID 37108784, 2023). "In addition to CDKN1A, HEB and E2A co-occupy three TSG loci, APC, a haplo-insufficient tumor suppressor, ZMYND11 a chromatin reader and tumor suppressor in breast cancer and CUX1, a homeodomain transcription regulator and haploinsufficient tumor suppressor." (PMID 35401501, 2022). "Two germline mutations were detected only in the older breast cancer patients but not in their younger counterparts: ATM [2/61; 3%] and APC [1/61; 1,6%] pathogenic mutations." (PMID 35127508, 2021). "Unlike in breast cancer samples, Wnt activity determined by Axin2 was inversely correlated to YAP-mediated transcriptional activity in CRC samples, particularly in APC or CTNNB1 mutated cancer samples." (PMID 34298652, 2021). "To summarize, we speculate that 5′-tiRNAVal plays a role in breast cancer chemoresistance through FZD3, β-catenin, c-myc, and APC." (PMID 33072328, 2020). "Wnt pathway activity scores were normal in the reference (WT), increased in loss-of-function APC-mutated ovary cancer and in gain-of-function CTNNB1 Asp32Tyr mutated breast cancer, and normal in non-functionally mutated CTNNB1 Asp665Glu breast cancer." (PMID 33613616, 2020). "Based on the correlation of APC and METTL14, ZC3H13 in breast cancer, we speculated that METTL14 and ZC3H13 were indirectly involved in mediating tumor immune responses." (PMID 33363011, 2020). "Unlike colorectal cancers, breast cancers present no mutations of molecules involved in the WNT pathway, such as adenomatous polyposis coli (APC) or β-catenin." (PMID 29854300, 2018). "We did not observe an interaction between RPA, APC methylation, and breast cancer-specific mortality (p = 0.138)." (PMID 28222775, 2017). "Thirdly, we did not retrieve articles related with APC methylation in different subtypes of breast cancer." (PMID 27191268, 2016). "Publically available algorithms (miRanda, TargetScan) were used to explore the precise mechanism by which miR-1229 activates the Wnt/β-catenin pathway in breast cancer, and showed that GSK-3β, APC, and ICAT might be potential targets of miR-1229." (PMID 26992223, 2016). "Genetic mutations of APC or the β-catenin encoding gene CTNNB1, which are the major causal factors for hepatic and colorectal cancers, are not typically associated with breast cancer." (PMID 27420097, 2016). "Approximately 6% of breast tumors contain mutations in the APC gene and thus far there are no reports indicating CTNNB1 mutation in cases of breast cancer." (PMID 27420097, 2016). "Importantly, the only regions that displayed a positive correlation between methylation and expression among the breast cancers in the TCGA database were four far-upstream or intragenic regions for the genes EN1, PITX2, APC and LHX2." (PMID 26510686, 2015). "Methylation-sensitive high-resolution melting was used to screen promoter methylation in a panel of 13 genes reported as methylated in breast cancer (RASSF1A, TWIST1, APC, WIF1, MGMT, MAL, CDH13, RARβ, BRCA1, CDH1, CDKN2A, TP73, and GSTP1) in 29 tumour pairs (16 ipsilateral and 13 contralateral)." (PMID 26452468, 2015). "The most frequently methylated genes were RASSF1 (65%), APC (43%), CDH13 (35%), GSTP1 (17%), and CDKN2B (17%), and the pattern was quite similar in breast carcinomas from mutation carriers, non-carriers and sporadic ductal cases." (PMID 22691310, 2012). "In this study, aberrant methylation of RASSF1, APC and GSTP1 were both frequent as well as early events in the progression continuum from normal to benign to invasive cancer and support a monoclonal transformation continuum to breast cancer progression." (PMID 21776373, 2011). "Furthermore, promoter hyper-methylation of APC and RASSF1 has been demonstrated to be a significant prognostic factor for the survival of breast cancer patients." (PMID 20544021, 2010).
breast cancer (continued). "Normal tissue adjacent to breast cancer displayed statistically significant differences to unrelated normal breast tissues regarding the aberrant methylation of the RASSF1A (P = 0.03), RARβ2 (P = 0.04) and APC (P = 0.04) genes." (PMID 20226036, 2010). "APC was hypermethylated in 29%, RASSF1A in 35% and ESR1 in 20% of breast cancer cases." (PMID 19367284, 2009). "We are currently testing this by sequencing the APC gene around codons 1500–1700 in hereditary breast cancer patients which tested negative for BRCA1/BRCA2 germline mutations." (PMID 19578404, 2009). "This study represents the first comprehensive comparison of the frequencies of APC gene promoter hypermethylation in the inflammatory and non-inflammatory breast cancer phenotype." (PMID 18841156, 2008). "DNA methylation of APC in serum of early breast cancer patients who had not undergone adjuvant systemic treatment appeared to be an independent prognostic marker for overall survival." (PMID 18841156, 2008). "Promoter hypermethylation is a well-known mechanism of transcriptional repression of tumor suppressor genes in breast cancer, including BRCA1, APC, CDH1, FANCF, among others, and may provide a complementary pathway of molecular carcinogenesis, independent of mutations." (PMID 33227964, 2020). "miR-135b reduces the proliferation of ERα-positive BC cells, but promotes the proliferation and invasion of triple-negative breast cancer (TNBC) by downregulating APC expression." (PMID 33679865, 2020). "Importantly, individual silencing of GSK-3β, APC, or ICAT dramatically increased the rate of cell proliferation and growth, further demonstrating that GSK-3β, APC, and ICAT are essential effectors of miR-1229–induced breast cancer cell proliferation." (PMID 26992223, 2016). "The localization of APC and β-catenin was analyzed in multiple cell lines, including non-transformed epithelial lines treated with a proteasome inhibitor or TGFβ to induce an epithelial-to-mesenchymal transition (EMT), as well as several breast cancer lines, by immunofluorescence." (PMID 23302090, 2013). "For breast cancer, some of the genes reported to undergo hypermethylation are involved in evasion of apoptosis (DAPK, TWIST1, HOXA5), cell cycle regulation (p16, CCND2), cell invasion and metastasis (CDH1, APC), DNA repair (BRCA1) and cell signaling (ER and RARβ2)." (PMID 20226036, 2010). "The APC protein expression in breast cancer was independent of the APC methylation level." (PMID 18841156, 2008). "Furthermore, specific DNA methylation biomarkers, including epigenetic modifications in APC, RASSFI, and FOXA1, are emerging as promising candidates for a gene panel that could facilitate the early detection of breast cancer via non-invasive liquid biopsy methodologies." (PMID 40994935, 2025). "Interestingly, exomiR-1229 was found to be upregulated in breast cancer and to trigger tumorigenesis by activating the Wnt/β-catenin pathway following targeting the key negative regulators of β-catenin such as glycogen synthase kinase (GSK)-3β, adenomatous polyposis coli (APC), and ICAT." (PMID 36900356, 2023). "However, APC promoter methylation may not be suitable for screening and diagnosing breast cancer alone due to the low sensitivity (OR = 0.444)." (PMID 27191268, 2016). "DNA promoter methylation of a gene panel including APC, CCND2, RARB, RASSF1A, and SCGB3A1 in breast cancer samples was not correlated with age in a previous study." (PMID 27028854, 2016). "Median PMR values of APC and RASSF1A, but not of ESR1, were significantly higher among breast cancer cases as compared with controls (P<0.05)." (PMID 19367284, 2009). "Double negative (ER-negative, HER2/neu-negative) breast cancers had significantly lesser frequencies of RASSF1A, GSTP1, and APC methylation (P < 0.0001, P < 0.0001, and P = 0.0035, respectively)." (PMID 18485221, 2008).
breast cancer (continued). "Double-negative breast tumors exhibited frequent hypermethylation in APC, GSTP1, RASSF1A, and TWIST, revealing the presence of epigenetic differences between double-negative breast tumors and breast cancers expressing either HER2/neu or ER." (PMID 18485221, 2008). "Although the role of the APC gene, which is central in the β-catenin/WNT pathway of carcinogenesis in human breast cancer is emerging, neither APC mutant mice nor humans carrying germline mutations in APC develop spontaneously mammary cancer in a high percentage." (PMID 25831236, 2015). "Since APC has been shown to control the G1/S transition by regulating the β-catenin/TCF transcriptional targets c-myc and cyclin D1, these results suggest that APC suppression in these invasive breast cancer cells impacts neither β-catenin-mediated transcription nor proliferation." (PMID 23302090, 2013).
colorectal tumors (145 papers, 1994 to 2025). "Curiously, most colorectal tumors carry biallelic mutations that result in only partial loss of APC function, suggesting that a “just-right” level of APC inactivation, and hence WNT signaling, provides the optimal conditions for tumorigenesis." (PMID 41091816, 2025). "Through NGS analysis of colorectal neoplasms, we identified the genetic profile of the colonic adenoma-carcinoma sequence and the high prevalence of APC somatic mutations in colorectal tumors from both FAP patients and sporadic cases." (PMID 41488735, 2025). "Mutation or loss of the APC gene can lead to dysregulated cell cycle, thereby promoting the occurrence of colorectal tumors." (PMID 39439901, 2024). "For example, APC mutations are rate-limiting for colorectal tumor initiation, suggesting that APC is an “initiation gatekeeper”." (PMID 35626065, 2022). "Most colorectal tumors are caused by adenomatous polyposis coli (APC) loss-of-function mutations or β-catenin gain-of-function mutations, both of which result in abnormal Wnt signaling activation." (PMID 35846281, 2022). "We analyzed the mutations of 396 patients with colorectal tumors; 66.67% of them had mutations in the APC gene." (PMID 35303016, 2022). "The oncogenic applications of APC inhibitor-related research are paramount, with 80–85% of sporadic colorectal tumors being exclusively associated with APC mutations." (PMID 36003330, 2022). "The Wnt/β-catenin signaling pathway is hyperactivated in approximately 90% of human colorectal tumors most frequently due to the mutually exclusive mutation of tumor suppressor genes APC or AXIN or of the CTNNB1 oncogene." (PMID 33910596, 2021). "We also know that colorectal tumors with APC loss of function are transcriptionally distinct from colorectal tumors with hyperactivated Wnt signaling caused by other non-APC–mediated mechanisms." (PMID 34000297, 2021). "Previous studies have shown that most of the mutated APC genes in colorectal tumors lack β-catenin-binding regions and fail to inhibit Wnt signaling, leading to overproliferation of tumor cells." (PMID 34631691, 2021). "Clinical data show that a large fraction of colorectal tumors with genetic alterations in APC express at least one truncated APC variant, which retains one to three 20AAR repeats able to bind and partially control β-catenin." (PMID 32586342, 2020). "Wnt signaling is ubiquitously activated in colorectal tumors and driver mutations are identified in genes such as APC, CTNNB1, RNF43 and R-spondin (RSPO2/3)." (PMID 33202731, 2020). "It has been observed that close to 85% of colorectal tumors has a loss-of-function mutation in APC whereas 50% of colorectal tumors which lack an APC mutation have activating mutation in β-catenin." (PMID 32922954, 2020). "Mutations in Adenomatous Polyposis Coli (APC) gene and/or its hyper-methylation are events common to ~80% of sporadic colorectal tumors and often represent the driver event for further occurrence of mutations." (PMID 32481626, 2020). "Whereas the majority of human colorectal tumors harbor truncated APC, the null variant of the APC gene is relatively uncommon." (PMID 31614493, 2019). "The early stages of colorectal tumors are predominantly associated with mutations in the tumor suppressor adenomatous polyposis coli (APC), resulting in aberrant activation of the Wnt signaling pathway." (PMID 31614493, 2019). "For instance, the APC mutation in the colorectal tumor crc3913 clearly occurred before the 5q CN-LOH because it was present on both copies of chromosome 5q." (PMID 31416464, 2019). "Approximately 90% of sporadic colorectal tumors carry a mutation in APC and up to 5% in the CTNNB1 gene." (PMID 31614493, 2019). "Mutation of the APC gene occurs in a high percentage of colorectal tumors and is a central event driving tumor initiation in the large intestine." (PMID 30131849, 2018).
colorectal tumors (continued). "Among the early events in the FAP tumor progression pathway is the lack of the APC gene, a TSG, which appears to be consistent with its essential role in predisposing individuals with germ line APC mutations in colorectal tumors." (PMID 28331559, 2017). "A wealth of data shows that almost all colorectal tumors with APC mutations lose the SAMP (connexion/actin/β-catenin binding) repeats and all,or otherwise one or two of the seven β -catenin binding/degradation sites." (PMID 28576136, 2017). "EphB6 overexpression together with APC gene mutations was suggested to promote the development of colorectal tumors." (PMID 29299148, 2017). "According to a recent review, the β-catenin signaling activity (β-catenin reporter activity) was low (between 10–20%) for APC mutations in breast tumors, versus moderate to high (between 20–100%) in colorectal tumors." (PMID 27218469, 2016). "APC mutations have been subsequently found in ~80% of sporadic colorectal tumors, confirming that APC acts as a central gatekeeper protein in colorectal tumorigenesis." (PMID 26056602, 2015). "This mouse tumor model resembles human colorectal tumors which commonly harbor mutations that activate Wnt signaling, generally through common mutations in APC and occasionally β-Catenin." (PMID 25162504, 2014). "APC*I1307K (c.3920T>A) is an inherited variant associated with colorectal tumour risk found almost exclusively in those of Ashkenazi Jewish ancestry." (PMID 24416237, 2014). "In contrast, Rac1 levels are normal in colorectal tumors, but truncated mutants of adenomatous polyposis coli (APC), which is the cause of sporadic and familial colorectal tumors, stimulate the activity of Asef, a Rac-specific guanine exchange factor." (PMID 24646293, 2014). "In colorectal tumor cells, the tumor suppressor gene APC is frequently affected by loss of heterozygosity (LOH) as well as mutations, resulting in inactivation of the APC protein complex targeting β-catenin for degradation." (PMID 24467841, 2014). "Cancer epidemic analysis showed that APC mutations were also found in approximately 80% of sporadic colorectal tumors." (PMID 22432006, 2012). "Colorectal tumours are characterized by mutations in wnt pathway signalling components, principally APC and β-catenin, leading to disregulated or cell-autonomous responses to wnt." (PMID 21829496, 2011). "Mutations in the APC gene occur in ∼80% of colorectal tumours and often result in a truncated APC protein which disrupts the WNT signalling pathway." (PMID 19878146, 2010). "The APC gene (chr5q21) is mutated in most colorectal tumours and its usual mode of LOH is mitotic recombination." (PMID 19515250, 2009). "It is notable that some microsatellite stable colorectal tumours do indeed present with frameshift mutations in repetitive regions of APC." (PMID 19436735, 2009). "The recombination and gain/deletion breakpoint maps on 5q were not, however, associated, perhaps owing to selective constraints on APC dosage in early colorectal tumours." (PMID 19515250, 2009). "Somatic APC mutations also occur in up to 85% of sporadic colorectal tumours and a similar association between "first hit" and "second hit" is seen." (PMID 19515250, 2009).